RNU6-259P (RNA, U6 small nuclear 259, pseudogene)
Gene: Small nuclear RNA gene on chromosome 2 (124,989,219 to 124,989,325, forward strand). Ensembl gene ENSG00000206726.
Homologues: Orthologues: chimpanzee U6 (98% identical), macaque U6 (97% identical). Paralogues in human: RNU6-589P (93% identical), RNU6-1152P (91% identical), RNU6-166P (90% identical), RNU6-41P (90% identical), RNU6-44P (90% identical), RNU6-1060P (89% identical), RNU6-116P (89% identical), RNU6-15P (89% identical), RNU6-19P (89% identical), RNU6-211P (89% identical), RNU6-35P (89% identical), RNU6-393P (89% identical), and 1285 more.